MARCKS (myristoylated alanine rich protein kinase C substrate)
Diseases named in the same sentence as MARCKS in open-access papers (continued):
Sharing a sentence is not in itself a finding about the gene and the disease.
ovarian carcinoma (7 papers, 2016 to 2022). A malignant neoplasm originating from the surface ovarian epithelium. "Highly expressed MARCKS contributes to stromal cancer-associated fibroblast activation and promotes ovarian cancer metastasis, which is associated with poor patient survival." (PMID 31058089, 2019). "In ovarian carcinoma, in silico analysis of a large transcriptomic database showed that high MARCKS mRNA expression was associated with poor patient survival." (PMID 28009981, 2017). "Importantly, we highlighted the association of MARCKS protein expression with poor OS in uni- and multivariate analyses, whereas the only other published study in ovarian cancer showed the association of MARCKS overexpression with poor OS only at the mRNA level and without multivariate analysis." (PMID 29295532, 2017). "ALDH1A3, MARCKS, and COL5A1 were associated with reduced survival across all 3 datasets underscoring their relevance to ovarian cancer disease." (PMID 31534498, 2019). "The authors found at the transcriptional level in a series of 3431 ovarian cancer specimens a small correlation between high stroma MARCKS expression and higher FIGO stage." (PMID 29295532, 2017). "In the literature, only one study analyzed MARCKS protein expression in epithelial ovarian cancer and found similar results." (PMID 29295532, 2017). "Firstly, in a co-culture system, we found that CAFs had an attenuated attractive effect in inducing SKOV3 and primary ovarian cancer cell migration after MARCKS knock down." (PMID 27081703, 2016). "Our results demonstrated that repression of MARCKS in CAFs impaired their ability to support the growth of cocultured ovarian cancer cells." (PMID 27081703, 2016). "Thus, our observation of association of stromal MARCKS expression in EOC with shorter OS is consistent with the clinical and pre-clinical findings published in ovarian cancer and many other cancers." (PMID 29295532, 2017). "As the developmental program epithelial-mesenchymal transition (EMT) correlates with malignant cells migration and chemosensitivity, we analyzed MARCKS expression with EMT associated signature genes and found a strong positive relationship between them in large profiling cohorts of ovarian cancer." (PMID 27081703, 2016). "Additionally, integrative analysis of MARCKS was conducted in the CSIOVDB dataset, which includes transcriptomic profiles of 3,431 ovarian cancer specimens." (PMID 27081703, 2016). "The role of MARCKS in the drug resistance of ovarian cancer has never been described." (PMID 35628654, 2022).
Alzheimer disease (6 papers, 2015 to 2025). A progressive, neurodegenerative disease characterized by loss of function and death of nerve cells in several areas of the brain leading to loss of cognitive function such as memory and language. "MARCKS has been investigated in the ageing brain, has been associated with frontotemporal lobar degeneration, and has been highlighted as a sex-specific biomarker for Alzheimer's disease." (PMID 41488750, 2025). "At early stages of Alzheimer’s disease, before the aggregation of extracellular Aβ, phosphorylation of MARCKS at Ser46 reflects neurite degeneration." (PMID 30225354, 2018). "Phosphorylation of myristoylated alanine-rich C kinase substrate (MARCKS) reflects neurite degeneration at the early stage of Alzheimer’s disease (AD), before extracellular Aβ aggregates are histologically detectable." (PMID 30225354, 2018). "To confirm these predictions, we performed an in vitro phosphorylation reaction of GST-MARCKS with candidate MAPKs, including JNK, which has been implicated in Alzheimer’s disease, and performed mass spectrometry to examine whether these kinases could actually phosphorylate MARCKS at Ser46." (PMID 27557632, 2016).
asthma (6 papers, 2016 to 2025). "Mitochondrial reactive oxygen species, glutathione S-transferases, arginase 1 and RORC in immune regulation, the Notch pathway, YPEL4 in cell proliferation, and MARCKS in airway mucus secretion play roles in asthma pathogenesis." (PMID 39858200, 2025). "The roles of epithelial miR-21 in asthma are uncertain, although a previous report indicates that miR-21 targets mRNA for MARCKS, a known regulator of airway mucin secretion." (PMID 27463381, 2016). "In a mouse model of asthma, peptide inhibition of MARCKS was shown to inhibit mucus hypersecretion and alleviate disease within the airway." (PMID 27073869, 2016). "Future studies could further explore the role of MARCKS in the pathophysiology of asthma and its potential as a therapeutic target." (PMID 39858200, 2025). "Moreover, a 24 aa peptide derived from the N-terminus of MARCKS was shown to block mucus secretion in a mouse model of asthma, further implicating MARCKS function in actin-mediated secretion." (PMID 28638804, 2017). "Therefore, further research is required to assess the precise mechanisms by which MARCKS and MARCKSL1 contribute to development and regeneration, providing professionals with the molecular tools that will help them design new therapies for illnesses such as asthma, cancer, and spinal cord injury." (PMID 29788979, 2018).
colon carcinoma (6 papers, 2016 to 2022). "For instance, in a mouse colon cancer model, MARCKS depletion reduces motility and invasion in vitro and significantly inhibits metastases in a syngeneic model of colon metastasis in vivo." (PMID 36230850, 2022). "Finally, inhibition of MARCKS phosphorylation sensitizes colon cancer cells to doxorubicin or 5-FU-based chemotherapy by decreasing ATP-binding-cassette transporter family member ABCB1 internalization, thereby reducing ABCB1 activity, a major cause of chemotherapy resistance in cancer." (PMID 36230850, 2022).
renal cell carcinoma (6 papers, 2019 to 2024). "Genetic and pharmacological suppression of MARCKS in high-grade renal cell carcinoma cell lines resulted in inhibited cell proliferation and migration." (PMID 38903524, 2024). "In high-grade renal cell carcinoma, genetic MARCKS inhibition by short interfering RNA or pharmacological inhibition by MANS leads to decreased cell proliferation and migration." (PMID 31058089, 2019). "After MARCKS knock-down in renal cell carcinoma cells, the efficacy of the tyrosine kinase inhibitor Regorafenib was enhanced, whereas MARCKS attenuation by MANS led to inactivation of AKT and mTOR." (PMID 31058089, 2019). "In renal cell carcinoma (RCC), MARCKS phosphorylation is positively correlated with tumor grade, and increased MARCKS expression promotes tumor growth and angiogenesis in vivo in an RCC xenograft model." (PMID 36230850, 2022). "In addition, MARCKS knockdown reduces phosphorylation of PI3K and AKT in non-small-cell lung cancer (NSCLC) cells and renal cell carcinoma (RCC)." (PMID 33578797, 2021).
inflammatory breast carcinoma (5 papers, 2017 to 2025). An advanced, invasive breast adenocarcinoma characterized by the presence of distinct changes in the overlying skin. "In a prior study, we showed that overexpression of MARCKS was correlated with the inflammatory breast cancer (IBC) phenotype." (PMID 29295532, 2017). "Inhibition of MARCKS has been shown to impair cell proliferation, invasion, migration, and mammosphere formation, and therefore, positioning it as a potential therapeutic target for 28% of MARCKS-positive inflammatory breast cancer patients." (PMID 39926275, 2025).
kidney cancer (5 papers, 2017 to 2025). Primary or metastatic malignant neoplasm involving the kidney. "The results of recent studies have demonstrated that MARCKS is associated with angiotensin II signaling in kidney cancer and plays a critical role in neo-angiogenesis." (PMID 40710334, 2025). "MARCKS was recently shown to be related to angiotensin II in kidney cancer and to play a key role in neo-angiogenesis." (PMID 36012380, 2022). "This leads to a decrease of kidney cancer cell survival, and demonstrates the potential of MARCKS as a possible druggable therapeutic target." (PMID 31058089, 2019). "Likewise, MARCKS is upregulated in kidney cancer, and genetic or pharmacologic MARCKS suppression leads to a decrease in cell proliferation and migration of renal carcinoma cells." (PMID 31058089, 2019). "Finally, in kidney cancer, MARCKS inhibition with MPS peptide synergistically interacted with regorafenib treatment and decreased survival of kidney cancer cells through inactivation of AKT and mTOR (mechanistic target of rapamycin)." (PMID 29295532, 2017).
metastatic disease (5 papers, 2013 to 2022). "It is therefore reasonable to presume that further experimental research is needed to identify inhibitory peptides or small molecules that systemically targets MARCKS and thus can be used to prevent metastatic disease." (PMID 36551563, 2022). "Taken together, the majority of the evidence points to a promoting role of MARCKS in cancer metastasis through multiple signaling pathways in most solid tumors, indicating MARCKS may serve as a potential therapeutic target to tackle metastatic disease." (PMID 36230850, 2022). "Second, using IHC analyses in a small series of 10 normal ovarian tissues and 18 pairs of primary and metastatic tumors from patients with advanced (stages III–IV) serous adenocarcinoma, they showed that MARCKS protein was highly expressed in ovarian tumor stroma versus epithelial cells compartment." (PMID 29295532, 2017).
neuroblastoma (5 papers, 2008 to 2020). Neuroblastoma (NB) is the most common solid, extracranial childhood tumor. "We overexpressed chicken MARCKS in neuroblastoma N2A cells along with a tetracycline inducible system for p35 over-expression." (PMID 24658276, 2014). "The results presented here confirmed that chick MARCKS is phosphorylated by murine endogenous Cdk5 when it, was overexpressed in neuroblastoma N2a cells, altogether with p35." (PMID 24658276, 2014). "Since mouse MARCKS-Ser27 is a homologue residue to chicken MARCKS-Ser25, we expressed chicken MARCKS in mouse N2A neuroblastoma cells." (PMID 24658276, 2014). "There was indeed a substantial PKC-mediated increase in MARCKS phosphorylation concomitant with TPA-stimulated migration indicating a role for MARCKS in the PKC-mediated motility of neuroblastoma cells." (PMID 19077250, 2008).
breast tumor (4 papers, 2015 to 2017). "First, elevated phospho-MARCKS abundance was positively correlated with poor differentiation and invasion/metastasis of breast tumors." (PMID 26015406, 2015). "Comparing to adjacent normal breast tissues, high phospho-MARCKS was detected in 86% (n = 18/21) of breast tumor specimens (left)." (PMID 26015406, 2015). "Five genes (SEMA3F, BLVRB, PTPRF, MARCKS, and CQQ6) are up regulated both in HER2 positive cell lines and in high HER2 expressing primary breast tumor tissues." (PMID 25428913, 2015).
cholangiocarcinoma (4 papers, 2012 to 2021). A carcinoma that arises from the intrahepatic biliary tree (intrahepatic cholangiocarcinoma) or from the junction, or adjacent to the junction, of the right and left hepatic ducts (hilar cholangiocarcinoma). "In cholangiocarcinoma, MARCKS overexpression correlated with poor survival, and experimental models showed the role of MARCKS in the migration of cholangiocarcinoma cells." (PMID 29295532, 2017). "Then, using experimental models, they reported MARCKS as one of the key players in the migration of cholangiocarcinoma cells and suggested that the cycling between MARCKS and phospho-MARCKS might regulate the metastasis of biliary cancer cells." (PMID 28009981, 2017).
Cognitive impairment (4 papers, 2015 to 2022). Abnormal cognition is characterized by deficits in thinking, reasoning, or remembering. "In addition to various neurodegenerative and cognitive disorders, several studies have recently demonstrated that the declining MARCKS levels that occur with age may underlie some forms of aging-related pathology." (PMID 26528135, 2015). "Future studies should investigate genetic interactions such as these, as well as potential roles for MARCKS in DS and other cognitive disorders involving dendritic spine pathology." (PMID 26528135, 2015). "Similarly, in APP-KI mice subcutaneous or intravenous injection of human antibody #129 recovered MARCKS phosphorylation at Ser46, decrease of dendritic spines, cognitive impairment, and extracellular Aβ aggregates." (PMID 34635772, 2021). "Subcutaneous or intravenous injection of human monoclonal anti-HMGB1-Ab #129 into 5xFAD mice suppressed MARCKS phosphorylation at Ser46 in immunohistochemistry and western blot analyses, recovered decrease of dendritic spines, and recovered cognitive impairment." (PMID 34635772, 2021).
gastric cancer (4 papers, 2016 to 2024). A primary or metastatic malignant neoplasm involving the stomach. "Studies demonstrated that MARCKS was a marker of poor prognosis in highly plastic gastric cancer." (PMID 38274323, 2024). "The results showed that MARCKS expression was elevated in gastric cancer cell lines MKN7 and MKN28." (PMID 38274323, 2024). "MARCKS aggravates gastric cancer tumorigenesis and progression via EMT pathway." (PMID 33976744, 2021). "Besides, MARCKS was a prognostic factor that inhibited the viability of gastric cancer cells." (PMID 38274323, 2024). "Finally, we carried out qRT-PCR analysis of the expression levels of RGS2, GNAI2, ANXA5, MARCKS, CD36, NRP1, and PDE4A in gastric cancer cells." (PMID 38274323, 2024). "Similarly, using bioinformatics analysis, another concurrent study has shown that a G2/M checkpoint-related signature composed of five genes (MARCKS, CCNF, MAPK14, INCENP, and CHAF1A) was connected with the prognosis of gastric cancer (GC) patients." (PMID 35419294, 2022). "In addition, a key EMT transcriptional factor, Twist1, was shown to be responsible for MARCKS action on CAF characteristics, similar to that Twist1 induced the transformation of normal fibroblasts in gastric cancer." (PMID 27081703, 2016).
leukemia (4 papers, 2016 to 2022). A malignant (clonal) hematologic disorder, involving hematopoietic stem cells and characterized by the presence of primitive or atypical myeloid or lymphoid cells in the bone marrow and the blood. "In THP-1 cells, three MARCKS alleles are present due to leukemia-associated abnormality." (PMID 36009319, 2022). "An increase in the expression of MARCKS was also observed in leukemia cells showing acquired resistance to other second-generation proteasomal inhibitors including, Salinosporamide A (Marizomib) and the immunoproteasome inhibitor PR924." (PMID 33958003, 2021). "Franke and colleagues reported an upregulated expression of MARCKS in bortezomib-resistant leukemia cells as well as refractory pediatric leukemia patients treated with bortezomib-based chemotherapy." (PMID 33958003, 2021). "In fact, in BTZ-resistant leukemia cells, MARCKs protein co-localized with intracellular vesicles that contained polyubiquitinated proteins and which were formed upon exposing cells to increasing concentrations of BTZ." (PMID 29071527, 2017). "Gene expression profiling of BTZ-resistant leukemia cells identified myristoylated alanine-rich C-kinase substrate (MARCKS) as being highly upregulated." (PMID 29071527, 2017). "Consistently, in leukemia cells we show here the upregulation of MARCKS protein in CEM/BTZ cells as well as CEM cells with acquired resistance to new generation proteasome inhibitors Marizomib and PR924." (PMID 27542283, 2016). "Using MEG-01, a model human megakaryoblastic leukemia cell line, the authors reported that different PKC isozymes impacted the initiation and maintenance of differentiation of the leukemia cells by regulating the phosphorylation and membrane localization of MARCKS." (PMID 33958003, 2021). "Of all genes, MARCKS (myristoylated alanine-rich C-kinase substrate) was the most differentially overexpressed gene with a 25- to 42-fold upregulation in the BTZ-resistant leukemia cell lines." (PMID 27542283, 2016). "Moreover, when MARCKS protein expression was demonstrated in specimens derived from therapy-refractory pediatric leukemia patients (n = 44), higher MARCKS protein expression trended (p = 0.073) towards a dismal response to BTZ-containing chemotherapy." (PMID 27542283, 2016). "Upregulation of MARCKs protein expression emerged as a marker for BTZ- and second-generation PI-resistant leukemia cell lines." (PMID 29071527, 2017). "MARCKS upregulation was confirmed on protein level and also observed in other BTZ-resistant tumor cell lines as well as in leukemia cells with acquired resistance to other proteasome inhibitors." (PMID 27542283, 2016). "Of note, unlike MM, phosphorylated MARCKS displayed a low basal expression in leukemia cells selected for drug resistance." (PMID 33958003, 2021). "MARCKs upregulation is not restricted to BTZ-resistant leukemia cells, but was also observed in leukemia cells with acquired resistance to second-generation PI, e.g., Salinosporamide A (Marizomib) and the immunoproteasome inhibitor PR924." (PMID 29071527, 2017). "Additionally, stimulated changes to the phosphorylation status of MARCKS also had no impact on the sensitivity of leukemia cells towards bortezomib treatment." (PMID 33958003, 2021). "Given the overexpression of MARCKS in BTZ-resistant leukemia cells, we explored whether or not MARCKS overexpression may serve as predictive marker of BTZ unresponsiveness in clinical samples of acute leukemia patients." (PMID 27542283, 2016). "However, unlike MM cells, in leukemia cells we noted marginal basal levels of MARCKS phosphorylation suggesting no major involvement in leukemia cells that were selected for BTZ resistance." (PMID 27542283, 2016).
pancreatic cancer (4 papers, 2012 to 2022). "Although the proteomic analysis does not directly detect the Wnt protein, high levels of WLS may be causative of inducing the secretion of Wnt, that promotes the activation of MARCKS and its downstream pathways in oxaliplatin-resistance pancreatic cancer." (PMID 33578797, 2021). "Taken together, our results provide insights into multiple mechanisms of oxaliplatin resistance in pancreatic cancer cells and reveal that MARCKS and WLS might be involved in the oxaliplatin resistance." (PMID 33578797, 2021). "Furthermore, MARCKS transcript levels are upregulated in chronic myelogenous leukemia quiescent stem/progenitor cells, and secreted MARCKS protein has been identified in pancreatic cancer stem cells." (PMID 36230850, 2022). "Furthermore, we demonstrated that both Wntless homolog protein (WLS) and myristoylated alanine-rich C-kinase substrate (MARCKS) could participate in oxaliplatin resistance in pancreatic cancer cells." (PMID 33578797, 2021).
schizophrenia (4 papers, 2010 to 2025). A major psychotic disorder characterized by abnormalities in the perception or expression of reality. "MARCKS, a protein involved in neurodevelopment and implicated in schizophrenia, is a D-cysteine binding protein." (PMID 41008577, 2025). "Further studies of Dysbindin and its association with MARCKS and with schizophrenia may reveal novel treatment targets for schizophrenia." (PMID 20098743, 2010). "Evidence for dysregulated N-myristoylation in schizophrenia is currently limited to findings related to the defective function, localization, or expression of key substrates of this modification, such as the protein MARCKS." (PMID 32123175, 2020). "We then focused on three genes; Myristoylated alanine-rich protein kinase C substrate (MARCKS), Phospholipase C beta 4 (PLCB4) and Synaptotagmin 1 (SYT1), because an accumulating number of reports point to the involvement of impaired neural transmission in the schizophrenia pathology." (PMID 20098743, 2010).